IL10 (interleukin 10)
Diseases named in the same sentence as IL10 in open-access papers (continued):
Sharing a sentence is not in itself a finding about the gene and the disease.
COVID-19 (continued). "Further studies are needed to elucidate whether exogenous administration of IL-10 or molecules able to act as adjuvant for the activation of anti-inflammatory IL-10 signaling may be beneficial for ameliorating COVID-19 and post-COVID-19 symptoms." (PMID 37359549, 2023). "In contrast, severe COVID-19 includes sustained expression of these markers with additional signatures including IL-6, IL-10, IL-18, IL-23, TNF, and eotaxin among others suggesting that specific timing and failure to resolve inflammatory responses are important factors in disease progression." (PMID 37491352, 2023). "IL-6, TNF-α, and IL-10 may especially be related to cytokine storms in neonates of mothers with COVID-19." (PMID 36979888, 2023). "Although some studies correlate cytokines such as IL-6 and IL-10 as predictors of COVID-19 severity, elevated IL-10 levels could act to moderate excessive inflammation even though it is not able to do so." (PMID 36969257, 2023). "In a recent study, it has been reported that depletion of gut microbiota in COVID-19 cohort was linked with increasing concentrations of TNF-α, CXCL10, CCL2 and IL-10 indicating that these taxa might have a role in reducing the ARDS associated cytokine storm." (PMID 37161621, 2023). "Most COVID-19 patients included in this study had lymphopenia, eosinopenia, neutrophilia, increased inflammatory and coagulation indexes, and augmented sNLRP3, IL-6 and IL-10 levels." (PMID 37215142, 2023). "Also, the cytokine storm, a feature of the more severe forms of COVID-19, is reflected in a sharp increase in interleukin 10 (IL-10) and TNF-α serum levels, which would depend on the expression of the respective genes." (PMID 36928185, 2023). "Serum levels of IL-10 increase during the early stages of the disease – when viral load reaches its peak – and may predict COVID-19 outcome." (PMID 37523305, 2023). "Furthermore, in a sample of 317 patients diagnosed with COVID-19, high serum levels of IL-17 and IL-2 and low levels of IL-4 and IL-10 appeared to constitute a cytokine profile of long COVID-19." (PMID 36992491, 2023). "The results showed that the elevation in levels of serum IL-10 and TLR-4 could be a potential diagnostic marker for lymphopenia in COVID-19 patients with (AUC = 0.66 ± 0.08; P value = 0.05) for IL-10 and (AUC = 0.73 ± 0.07; P value = 0.006) for TLR-4." (PMID 36864077, 2023). "We found that, while the EPs from HC inhibit IL-5 and IL-10 production, the EPs from COVID-19 patients failed in downregulating these two cytokines, suggesting that the composition of the EPs isolated from COVID-19 patients was supporting the ILC2 activation status." (PMID 37207201, 2023). "Based on these important findings, our results suggest that IL-10 cytokine may play a mechanistic role in the induction of IgG4 responses after booster COVID-19 vaccination." (PMID 38173725, 2023). "Thus, during the first infection wave, IL-8 was significantly (p<0.05) increased predominantly in patients with severe disease versus those with moderate COVID-19 and a tendency in the same direction was observed for IL-6, IL-10 and IFN-α2." (PMID 36817433, 2023). "Consistent with this, we found higher serum levels of Il-10 in COVID-19 patients with xerostomia." (PMID 36846089, 2023). "Interestingly, several studies have predicted poor outcomes in patients with COVID-19, suggesting that dysregulation of IL-10 can occur during states of excessive immune cell activation, such as the cytokine storm seen with SARS-CoV-2 infection." (PMID 37373402, 2023). "Our analysis revealed elevated cytokine levels of IL-10 in all patients diagnosed with COVID-19." (PMID 37759873, 2023). "Pro-inflammatory cytokines such as IL-1, IL-10, IL-6, and TNF- α were found in significant concentrations in COVID-19 individuals, causing a cytokine storm during SARS-CoV-2 infection, which has been linked to ARDS, multi-organ failure, and increased candidate risk." (PMID 36608055, 2023).
COVID-19 (continued). "Notably, other studies have also indicated that patients with COVID-19 have elevated levels of cytokines secreted by Th2 cells (such as IL-4 and IL-10), which inhibit the inflammatory response." (PMID 37112918, 2023). "Notably, other studies have also indicated that patients with COVID-19 have elevated levels of cytokines secreted by Th2 cells (such as IL-4 and IL-10), which normally inhibit the inflammatory response." (PMID 37112918, 2023). "A high incidence of lymphopenia, ranging from 67–75%, has been consistently reported among COVID-19 patients who have a severe illness; it may correlate with an increased quantity of cytokines such as IL-6, IL-10 or TNF (tumor necrosis factor)." (PMID 37754237, 2023). "Similarly, a previous study found that people with severe COVID-19 had increased levels of IL-10 in their bodies compared to healthy people and people with mild COVID-19." (PMID 38139439, 2023). "In addition, our previous longitudinal analysis of cytokine profiles in mild to critical COVID-19 patients revealed that cytokines such as IL10, CXCL9, CXCL10, and IL6 progressively increased with greater disease severity." (PMID 36798115, 2023). "Also, numerous studies have shown that COVID-19 patients have increased levels of IL-1β, IL-2, IL-6, IL-10, TNFα, IFNγ, and that these cytokines correlate with the severity of the disease." (PMID 36835858, 2023). "It has also been observed a strong association between IL-10 levels and COVID-19 severity and outcome, suggesting that IL-10 fails to adequately turn off the inflammation." (PMID 37359549, 2023). "Some studies have found that IL-10 can be used to predict poor outcome in COVID-19." (PMID 37969879, 2023). "Thus, we suggest that IL-10 is a potential therapeutic candidate for COVID-19 with ARDS, especially in SARS-CoV-2 infection complications with ARDS." (PMID 36914565, 2023). "In this scenario, stimulation of IL-10 signaling with PEG-IL-10 or other IL-10 stimulation might result in clinical benefit for patients with severe COVID-19." (PMID 37359549, 2023). "Studies had shown that PTEN can activate dendritic cells, B cells and T cells, which are innate immune cells, and secrete pro-inflammatory factors, including interferon (IFN), TNF-α and IL10, thus inducing the formation of the cytokine storm in patients with COVID-19." (PMID 37037848, 2023). "Numerous clinical studies have also revealed that elevated amounts of IL-10 in the serum of COVID-19 patients, alone or with IL-6, IL-12 or IL-1RA, may accurately predict progression to more severe form of disease and increased mortality." (PMID 37359549, 2023). "Lu proposed that the combined roles of IL-10 in promoting systemic inflammatory cytokine production and stimulating T-cell activation and proliferation in COVID-19 patients may contribute to a lethal immunopathological process." (PMID 37735372, 2023). "Although the canonical role of IL-10 is as an anti-inflammatory cytokine, there has been some evidence that in COVID-19 it may exert a pro-inflammatory effect." (PMID 36999030, 2023). "Based on these crucial findings, our results suggest that IL-10 cytokine may mechanistically contribute to the induction of IgG4 responses following booster COVID-19 vaccination." (PMID 38173725, 2023). "Moreover, significant positive association has been observed among increased IL-10, IL-23 and TNF-α in serum of COVID-19 patients." (PMID 37283736, 2023). "On the other hand, sP2X7R correlated significantly with IL-10, whose activity might rather unexpectedly be related to the potentiation of the inflammatory response aggravating disease course in COVID-19 patients." (PMID 37215142, 2023). "Notably, the correlations of T helper naïve and effector memory cells, T helper 1–17 cells, TNF, IL-10, IL-1β, IL-8, among others, showed differences between healthy controls and COVID-19 patients." (PMID 36861136, 2023).
COVID-19 (continued). "Also demonstrating this effect, IL-10 possibly regulated the Th17 profile in neonates of mothers with COVID-19 because the high levels of IL-6 detected generally act on the excessive increase of the Th17 profile." (PMID 36979888, 2023). "Thus, it should be noted that higher levels of IL-6 and lower levels of IL-10 are related to COVID-19 severity and worse prognosis." (PMID 36914565, 2023). "Several studies showed elevated levels of IL-10 predict poor outcomes in COVID-19 patients." (PMID 36864077, 2023). "In patients with severe forms of COVID-19 also a strong relationship between early overexpression of IL-10 and increased serum concentrations of IL-1 receptor antagonist (IL-1RA) and other proinflammatory molecules, including IL-6, IL-8 and C-reactive protein was observed." (PMID 37359549, 2023). "Thus, it is possible that this also occurs in patients with COVID-19, in which the combination of high-dose IL-10 and bacterial products drives an inflammatory cascade in COVID-19 patients." (PMID 37283736, 2023). "Furthermore, significant increases in serum IL-10 were found in severe and critical COVID-19 patients who experienced cytokine storms." (PMID 37283736, 2023). "Contrarily, patients with COVID-19 who were severely infected experienced an excessive release of cytokines and chemokines, such as interleukin (IL)-1, IL-2, IL-6, IL-7, IL-8, IL-10, granulocyte-colony stimulating factor (GCSF), and tumour necrosis factor-alpha (TNF-α)." (PMID 36679947, 2023). "Interestingly, decreased expression of IL-10 was observed after co-cultivation of PBMC from COVID-19 patients with dental pulp-derived MSC." (PMID 36901868, 2023). "Also, ROC curve showed accurate association between the increase of serum IL-10 and TLR-4 and lymphopenia among COVID-19 patients with AUC = 0.66 ± 0.08 and AUC = 0.73 ± 0.07 respectively." (PMID 36864077, 2023). "While, both IL-6 and IL-10, as well as serum IL-17A, showed an increasing trend in severe COVID-19 patients after one week of hospitalization suggesting that, in more severe patients, the inflammatory status and the release of cytokines is a more prolonged phenomenon." (PMID 35893398, 2022). "Because of the consistency of the increased IL-10 level in patients with severe COVID-19, IL-10 may be used for immediate cytokine evaluation for clinical manifestation and disease progression." (PMID 36016311, 2022). "Similarly, using severity, a total of 38 eligible studies were used for pairwise comparison between mild and severe COVID-19 cases for IL-10." (PMID 35572964, 2022). "COVID-19 respiratory distress begins with an early inflammation so that pulmonary compliance is reduced by activation of intercellular inflammatory pathways, cytokine synthesis, or storm (excessive release of IL-2, IL-6, IL-7, IL-8, IL10, and TNF-α)." (PMID 35656183, 2022). "We observed a modest positive correlation (R = 0.50) between the IFN-I score in PBMCs and plasma IL-10 levels, which may support an association between the strength of the IFN-I response and the suppressive IL-10 response observed in COVID-19 patients." (PMID 35064122, 2022). "Moreover, blockage of IL-10 has been postulated as a target for treatment of severe COVID-19 patients." (PMID 36672534, 2022). "As expected, circulating levels of IL-6 and IL-10 were higher in ICU COVID-19 patients." (PMID 35637483, 2022). "Further, IL-10 inhibits the activation of adaptive immunity by suppressing the function of antigen recognition on APCs, pointing to the possible role of IL-10 as the main driver of the immunosuppression observed in patients with COVID-19." (PMID 35572964, 2022). "In the present study we evaluated the changes in serum IL-6, IL-10, and IL-17A levels and the cytometric lymphocyte profiles in 144 COVID-19 patients at admission and after one week of hospitalization, also in relation to steroid treatment before hospitalization." (PMID 35893398, 2022).
COVID-19 (continued). "However, patients with severe COVID-19 had significantly higher levels of IL-10 than patients with mild COVID-19 and healthy patients." (PMID 35562935, 2022). "IL-6 and IL-10 have been recently described as COVID-19 severity predictors." (PMID 35740951, 2022). "Next, we investigated more deeply the interplay between IFNs and immune markers whose elevation in circulation has been associated with poor prognosis in COVID-19, including interlelukin (IL)-22, SAA, IL-10, IP-10, IL-6, IL-8, MIP-3α, IL-1RA, MIP-1α, TNF-α, MCP-1, and MCP-4 (39, 40, 43, –45)." (PMID 35217532, 2022). "Moreover, after nicotine+SARS-CoV-2 treatment, cells released high levels of TNFα, IL6, IL8, and IL10, similarly to what is observed in COVID-19 patients with high disease severity and mortality." (PMID 36012747, 2022). "Therefore, our primary aim was to investigate the association between found SNPs, IL-6 (rs1800796), IL-10 (rs1800896), TNF-α (rs1800629), and IFITM3 (rs12252) and the presence of post-COVID pain in individuals previously hospitalized by COVID-19." (PMID 36233516, 2022). "In addition, both serum IL-6 and IL-10 significantly declined after one week of hospitalization in mild and moderate COVID-19 patients." (PMID 35893398, 2022). "Firstly, higher IL-10 concentrations may reflect an extreme attempt to counteract severe inflammation in COVID-19." (PMID 36123740, 2022). "Recent research suggests that high IL-10 levels in severe COVID-19 patients indicate immunological activation and inflammation, implying that IL-10 may play a role in proinflammatory and immune-activating responses in COVID-19 pathogenesis." (PMID 36415655, 2022). "‘Interleukin-10 signalling’ pathway variants in IL10RB, CCR2 and CCR5 were also enriched in PRSe2 and may contribute to the development of severe COVID-19." (PMID 35770811, 2022). "IL-10 has been reported to be dramatically elevated in serum of severe/critical COVID-19." (PMID 36415655, 2022). "The lipoprotein dyslipidemia associated with COVID-19 severity (high TG and low total, LDL and HDL cholesterol) was inversely correlated with inflammatory biomarkers such as increased levels of serum CRP, IL-6, IL-8, and IL-10." (PMID 35956081, 2022). "Interestingly, IL-10-secreting Tregs, a lineage known to possess anti-inflammatory properties in the lung, were elevated in severe COVID-19 patients, compared to mild/moderate diseases." (PMID 35497875, 2022). "The levels of Eotaxin, Eotaxin-3 and IL-10 were exclusively elevated in severe SOT COVID-19 whereas IL-16, IL-1RA, IL-1α, MIP-1α and TNF-α, were solely increased in Non-SOT COVID-19 patients with severe disease, as compared to their respective mild/moderate group." (PMID 35075453, 2022). "Increased IL-6, MCP-1 and IL-10 have been detected in COVID-19 BALs compared to peripheral blood." (PMID 36211412, 2022). "Accordingly, we evaluated the levels of IL-17, IFN-γ, TNF-α, IL-10, IL-6, IL-4 and IL-2 in patients with clinical COVID-19 and long COVID-19, with cases classified as mild, moderate and severe, and associations with risk factors for sex, age and presence of comorbidities." (PMID 35846757, 2022). "The IL-6/IL-10 ratio describes the inflammatory potential in COVID-19." (PMID 39931658, 2022). "In our study, elevated levels of IL-6, IL-10, and CCL5 seemed to be remarkable biomarkers for differentiating patients with severe COVID-19 from AS and NI patients, suggesting an association with progression to severe COVID-19." (PMID 36287506, 2022). "Besides IL-16, the anti-inflammatory cytokine IL-10 was found elevated in severe COVID-19 patients, while decreased circulating INF-gamma levels were associated to lung fibrosis in COVID-19 patients." (PMID 36359311, 2022). "Studies have shown that severe COVID-19 is accompanied by hypercytokinemia with high levels of pro-inflammatory cytokines such as IL-6 and IL-1β as well as anti-inflammatory cytokines such as IL-4 and IL-10." (PMID 35007290, 2022).
COVID-19 (continued). "In a COVID-19 cohort, the depletion of several bacterial species (B. adolescentis, E. rectale and F. prausnitzii, known to play immunomodulatory roles in the human GI system) was linked to increased plasma concentrations of TNF-α, CXCL10, CCL2 and IL-10." (PMID 35956081, 2022). "Few investigations are available on the action of IL-10 in COVID-19." (PMID 36148228, 2022). "In addition, plasma concentrations of Th2 cytokines IL-4, IL-10 and IL-13 were also significantly upregulated in COVID-19 patients." (PMID 36307516, 2022). "However metformin has been found to reduce TNF-alpha, IL-6, and possibly boost IL-10 in females more than males, which is relevant to the pathophysiology of COVID-19." (PMID 36395143, 2022). "This may be the clinical significance of excessive production of IL-10 in the serum of COVID-19 patients." (PMID 36148228, 2022). "In the circulation of patients with COVID-19, IL-6 reaches its peak at advanced stages, on average after the second week of disease, and, notably, this increase is accompanied by peak concentrations of IL-10 and CRP." (PMID 35340805, 2022). "Similarly, a dramatic increase in interleukin 10 (IL-10) is also seen in people with severe COVID-19." (PMID 36233516, 2022). "IL-10 is an anti-inflammatory cytokine described to be elevated in patients with severe COVID-19." (PMID 36111789, 2022). "In conclusion, we observed that oral selenium supplementation could boost the response of SARS-CoV-2 anti-spike IgG antibodies, IL-6, and IL-10 following the immunization with the Janssen COVID-19 vaccine in BALB/c models." (PMID 36679902, 2022). "However, a more comprehensive study is required to define both the potential protective and pathological roles of IL-10 in COVID-19 immune-pathogenesis." (PMID 36148228, 2022). "A significant number of DEPs in the severe group were related to immune evasion (33 DEPs), including IL10, which may play a pathological role in COVID-19 severity proinflammation and T-cell exhaustion." (PMID 35177642, 2022). "In addition, it was also found that the plasma levels of IL2, IL7, IL10, IL-6, TNFα, and e lymphopenia were higher in patients with COVID-19." (PMID 35295802, 2022). "It has been suggested that COVID-19 patients show an elevated expression of inflammatory cytokines, such as serum interleukin-10 (IL-10), IL-6, and IL-1β, compared to those with less severe symptoms, indicating the role of cytokine storm in the intensity of disease symptoms." (PMID 35455977, 2022). "This is consistent with a prior study that found that increased IL-10 levels may have a proinflammatory and immune-activating role in COVID-19 progression." (PMID 35958594, 2022). "Similarly, a total of 38 eligible studies were used for pairwise comparison between mild and severe COVID-19 cases for IL-10, with a total of 1,981 subjects in the mild group vs. 1,731 in the severe group." (PMID 35572964, 2022). "This study provides important insights into immune modulating effects of IL-10 in COVID-19 and may provide valuable information regarding the further in vivo investigations." (PMID 36148228, 2022). "Strangely enough, the role of IL-10 is not fully known and somewhat ambiguous in COVID-19." (PMID 35966540, 2022). "The best test performance for differentiating bacterial/fungal secondary infections and COVID-19 and/or ECMO associated inflammation was achieved by IL-10 (ROC-AUC 0.84) and a multivariant step-wise regression model including CRP, IL-6, PCT, and IL-10 (ROC-AUC 0.93)." (PMID 36275812, 2022). "Moreover, T cell exhaustion was also observed, concomitant with the higher expression of PD-1 and increased serum IL-6 and IL-10 in patients who were infected by COVID-19." (PMID 35271463, 2022). "Current detection for COVID-19 is primarily relies on techniques including, RT-PCR, chest X-ray, computed tomography (CT) scans, blood-based biomarkers (elevated C-reactive protein, low lymphocyte counts, high interleukins (IL-6/IL-10))." (PMID 36045375, 2022).